IL6 (interleukin 6)
Diseases named in the same sentence as IL6 in open-access papers (continued):
Sharing a sentence is not in itself a finding about the gene and the disease.
COVID-19 (continued). "We aimed to explore the relationship between baseline CT findings and inflammatory conditions and to evaluate the prognostic value of chest CT scores and laboratory findings in COVID-19 patients specifically treated with anti-IL-6." (PMID 37218940, 2023). "Interleukin 6 (IL-6) has been regarded as a biomarker that can be applied as a predictor for the severity of COVID-19-infected patients." (PMID 36679421, 2023). "Tocilizumab, an antibody that blocks IL-6, reduces inflammation and decreases the mortality rate in COVID-19 patients." (PMID 38127882, 2023). "Elevated levels of IL-6 have been identified as a major factor in the exacerbation of the COVID-19 inflammatory response, contributing to vascular inflammation, acute respiratory distress syndrome development, and mechanical ventilation." (PMID 37238657, 2023). "A recent study highlighted that active tryptase and IL-6 levels are higher in patients with post-acute sequelae of COVID-19 compared to patients with post-acute asymptomatic COVID-19, denoting MC activation." (PMID 37511729, 2023). "The lungs of patients with severe COVID-19 are abundant in highly inflammatory macrophages, which secrete inflammatory mediators like IL-1β, IL-6, IL-8, CXCL10, TNF-α, and other chemokines, further exacerbating the occurrence of cytokine storms." (PMID 37163438, 2023). "In COVID-19-derived monocytes, TNFα, IL1β, IL6, IL10, CXCL8/IL8, and COX2 were also significantly increased, depending on disease severity." (PMID 37310504, 2023). "We found that the EVs of COVID-19 patients contained higher levels of IL-6, TNFα, IL-2, and INFΥ compared to HCs." (PMID 36982991, 2023). "The key targets in the PPI network also present in the “Coronavirus disease - COVID-19” pathway included IL6, MAPK1, JUN, F2, and TNF." (PMID 38050310, 2023). "It is generally believed that the imbalance in Th1 and Th2 responses in COVID-19 patients triggers a cellular inflammatory storm, and increase the levels of inflammatory mediators such as interleukin IL-4, IL-10, and IL-6 in tissue samples." (PMID 37180704, 2023). "In the COVID-19 patients, 27 patients had IL-6 results of >25 pg/mL on admission and, later, 19 required mechanical ventilation (70.4%)." (PMID 36983566, 2023). "After recovery from COVID-19, the levels of circulating pro-inflammatory IL-6 decreased after 7 months and, moreover, 12 months of follow-up." (PMID 37896963, 2023). "In summary, IL-6 plays a pivotal role in the establishment of a hyperinflammatory milieu that leads to ARDS in patients with severe COVID-19, since it controls the transcription of various cytokines and growth factors involved in inflammation and fibrosis." (PMID 36791125, 2023). "A major modulator of the acute inflammatory response in ARDS and CRS, the pro-inflammatory cytokine IL-6 also appears to play a role in severe COVID-19 and contributes to increased C-reactive protein levels, hypercoagulation, and hyperferritinemia." (PMID 37649125, 2023). "The onset of CSS dysregulates the IL-6 pathway and plays a pivotal role in COVID-19 pathophysiology." (PMID 37243203, 2023). "Post-COVID-19 exhibited lower levels of serum IL-6 (p adj <0.01), whereas it showed higher serum IL-10, triglyceride, leptin, IgG, ACE activity, TNFRSF1A, and PGE2 (p adj <0.05) levels compared with controls." (PMID 37753077, 2023). "IL-6 is also elevated in the bronchoalveolar lavage (BAL) fluid of patients with severe COVID-19 compared with healthy controls and in severe compared to moderate disease." (PMID 37111341, 2023). "Vaccination against COVID-19 has been shown to increase IL-6 levels with an early small peak 1 day after vaccination." (PMID 36835948, 2023). "The key cytokines produced by the immune system in patients with severe COVID-19 are interleukins (IL-1, IL-2, and IL-6), TNF-α, and interferons (IFNs)." (PMID 37240319, 2023).
COVID-19 (continued). "Accordingly, upregulation of these regulatory immune subtypes was associated with lower levels of proinflammatory cytokines, in particular IL-6 and IL-1β, in the blood of treated severe COVID-19 patients." (PMID 37833265, 2023). "BARI is a selective inhibitor of Janus kinase (JAK) 1 and 2, and BARI treatment suppresses interleukin-6 or IFN-γ secretion in COVID-19 patients." (PMID 36896132, 2023). "This type of immunomodulatory approach has clinical precedent; in a trial of hospitalized COVID-19 patients with hypoxia and systemic inflammation, subjects who received the IL-6 blocker tocilizumab had improved outcomes." (PMID 37681974, 2023). "Data from 89 hospitalized COVID-19-infected patients are analyzed, and this study finds that the optimal cutoff for the maximal IL-6 level is 80 pg/mL for the prediction of respiratory failure." (PMID 36679421, 2023). "IL-6 testing became common practice in 2020 as an early marker of severe inflammatory response, COVID-19 severity, and as a criterion for the initiation of IL-6 inhibitor therapy." (PMID 37363429, 2023). "Key proinflammatory interleukins in COVID-19, IL-6, and IL-1, also interact with the platelet–thrombosis pathway." (PMID 36979908, 2023). "For instance, IL-1 antagonist (anakinra) and IL-6 antagonist (tocilizumab) are supposed to be promising treatments as well as cortisones for COVID-19." (PMID 37046952, 2023). "The fact that participants with the AA genotype of the ApaI rs7975232 polymorphism in this study had a greater death rate suggests that Th2 can also release Interleukin-6 (IL-6), which is related to COVID-19 prognosis." (PMID 36869206, 2023). "This study demonstrated that serum IFN-α levels present a higher OR in regard to the development of hypoxemia in the early phase of COVID-19 than those of other biomarkers, including IL-6." (PMID 37731495, 2023). "An increase of interleukin-6 in peripheral blood is a key risk factor and an early indicator of CRS in COVID-19." (PMID 36909058, 2023). "This observational study’s objective aimed to compare the IL-6 levels between mild and moderate COVID-19 patients according to the kind (quantitative or qualitative) of taste disorders." (PMID 35801415, 2023). "Comparing different groups of COVID-19 patients with a healthy control group, the levels of IL-6, serum ferritin, CRP, and ESR demonstrated significant differences." (PMID 37363608, 2023). "The activity of IDO was inversely related to IL-6 levels in COVID-19 patients, but the acylcarnitines, kynurenine, and methionine sulfoxide metabolites were positively correlated with IL-6 levels." (PMID 36991597, 2023). "There was a conclusive theoretical basis for targeting IL-6 by tocilizumab in COVID-19 with positive early case reports and small series." (PMID 37507425, 2023). "A therapeutic intervention that substantially decreases the viral load can decrease IL-6 levels and thus, the rate of simulated COVID-19-related events." (PMID 37059734, 2023). "Specifically, IL-6 has been found to be particularly important in the pathogenesis of COVID-19, since it is positively correlated with disease stages and radiological changes." (PMID 37623458, 2023). "Uncontrolled activation of macrophages not only leads to the secretion of high levels of IFN‐γ, IP-10, IL-6, IL-17, IL-10/23 and TNF-α but also causes a loss of inflammatory coordination mediated by type-I interferons, which is a hallmark of COVID-19." (PMID 37817178, 2023). "Along the same lines, patients with long-standing COVID-19 have been reported to have a pro-inflammatory cytokine profile characterized by higher levels of IL-1β, IL-6, IL-13, IL-17A, TNFα, IFNγ-induced protein-10 (IP-10), and G-CSF." (PMID 36836568, 2023). "Regarding multiple linear regression analysis in COVID-19, CRP, IL-6, and leucocytes (each p < 0.05) were associated with the degree of pulmonary infiltrates, as opposed to DPP3 (p = n.s.)." (PMID 37733154, 2023).
COVID-19 (continued). "IL-6 is predominantly relevant as its elevated plasma levels in COVID-19 patients are directly related to the severity of the disease." (PMID 37238657, 2023). "Several studies showed that IL-6 is better at reflecting the severity of the clinical presentation of COVID-19 and is relatively more consistent than other inflammatory markers." (PMID 37889917, 2023). "Our study found that, according to CCI, COVID-19 patients with several comorbidities had higher levels of IL-6 at day 1, day 2, and day 3 and lower levels of sIL-6R at day-1 only." (PMID 37887780, 2023). "Examples of PD DDIs in COVID-19 relate to the use of multiple medications such as interleukin-6 (IL-6) inhibitors, Janus kinase (JAK) inhibitors, and corticosteroids that can all cause immunosuppression." (PMID 37368815, 2023). "Consistent with the association between plasma IL-6 and CTL dysfunction in patients with COVID-19,35,36,37,38 we identified polyfunctional effector CTLs almost exclusively in cancer patients with low plasma IL-6." (PMID 36599350, 2023). "We validated previously published data that IL-8 chemokine and IL-6 and IL-10 cytokines were abundantly present in acute COVID-19 patients." (PMID 37228606, 2023). "In fact, elevated levels of SM (24:1) were positively correlated with clinical and inflammatory indicators in COVID-19, including the clinical score, hospitalization days, and neutrophil count, as well as the production of IL-10, IL-6, and IL-8." (PMID 37566018, 2023). "The results of univariate analyses showed that age, NEW score, Charlson comorbidity index, IL-6, ferritin, and CRP concentration, WBC and neutrophil count, NLR, LDH on admission, and Ct values ≤30 from SSs were associated with severe COVID-19." (PMID 37213664, 2023). "Both ACE-2 and IFITM-3 SNPs were amongst the highest determinants of COVID-19 severity, together with IL-6, CRP, D-dimer, ferritin, preexisting comorbidities, and age." (PMID 38155729, 2023). "This is the first observational study that analyzed IL-6 levels in COVID-19 patients with only taste dysfunction." (PMID 35801415, 2023). "IL-1 antagonists, such as anakinra, and IL-6 inhibitors, such as tocilizumab, have been used to treat cytokine storm syndrome in COVID-19 patients." (PMID 37046952, 2023). "The cytokine storm and enhanced level of IL-6 in the blood are considered predictive of a fatal outcome in severe COVID-19 patients." (PMID 36755327, 2023). "Incubation of platelets from COVID-19 patients with monocytes from healthy donors triggers the release of IL-1β, IL-6, IL-8, MIP-1α, MCP-1, TNF-α, PF4, and PDGF, and elevated levels of these factors were observed in clinical samples from COVID-19 patients." (PMID 38069209, 2023). "In contrast, lower omentin levels were seen in patients with COVID-19 and omentin was thought to reduce IL-6 and other inflammatory cytokines in COVID-19." (PMID 37676889, 2023). "IL-6 levels in COVID-19 patients are correlated between two different biomarker platforms but the absolute IL-6 levels were consistently higher in samples measured using Roche versus the Meso Scale Discovery device." (PMID 37650680, 2023). "Immunomodulatory drugs including steroids and interleukin 6 (IL-6) inhibitors are now recommended to manage dysfunctional hyperinflammation in severe COVID-19." (PMID 37978457, 2023). "TNFα and IL-6 are reported to play key roles in cytokine storms and are likely to be responsible for the escalation in disease severity of COVID-19." (PMID 38143504, 2023). "In COVID-19, higher vitamin D levels correlate with lower interleukin 6 levels, which are important targets for controlling cytokine storms." (PMID 36986216, 2023). "The results of this work also highlight the central role of IL-6 in the pathogenesis of both CVDs and COVID-19." (PMID 36768701, 2023). "Fedullo, Schiattarella found that diabetes patients infected with COVID-19 had higher concentrations of IL-6." (PMID 37893490, 2023).
COVID-19 (continued). "This immune response is characterized by the overproduction of cytokines, particularly Interleukins IL-1 and IL-6, which play a crucial role in the development of severe COVID-19." (PMID 37046952, 2023). "The most striking result revealed in this study was the decreased level of IL-6 in COVID-19 patients following SARS-CoV-2 vaccination." (PMID 37144176, 2023). "More data from ongoing randomized controlled trials are needed to understand the impact of IL-6 inhibitors in the management of COVID-19." (PMID 37163438, 2023). "IL-6 (significantly elevated in SIRS of COVID-19) has also been shown to induce cholestatic effects and inflammatory/fibrotic changes in the biliary epithelium." (PMID 37842470, 2023). "Compared with the control subjects, statistically significant differences were found for the mild and severe group patients, suggesting a positive relationship between the IL-6 concentration and the severity of COVID-19." (PMID 37363608, 2023). "The role of serum IL-6 as a marker of disease progression in critically ill COVID-19 patients after admission to the intensive care unit was known from early case reports." (PMID 37937220, 2023). "B cells from patients with acute COVID-19 displayed an IL-6 cytokine imbalance in response to Toll-like receptor activation, skewed toward a proinflammatory phenotype." (PMID 37095536, 2023). "Although in vitro treatment of COVID-19 plasma with low molecular weight heparin (LMWH) and heparan sulfate mimetic minimised glycocalyx perturbation, and LMWH was shown to reduce IL-6 levels in COVID-19 patients." (PMID 37147421, 2023). "Because COVID-19 causes a cytokine storm by increasing pro-inflammatory cytokines such as TNF-α, IL-6, and IL-1β, we also analyzed these cytokine levels in the media of cells treated without or with the RBD for 24–120 h." (PMID 36982738, 2023). "In COVID-19 patients with myocardial injury, the level of IL6 increased while the lymphocyte count decreased." (PMID 37564653, 2023). "In fact, all patients who required subsequent ventilation had IL-6 levels on admission ranging between 25 and 120 pg/mL pg/mL; thus, of the 27 COVID-19 patients who had IL-6 results >25 pg/mL on admission, 19 of them later needed mechanical ventilation)." (PMID 38203482, 2023). "Although the serum IL-6 levels of all COVID-19 patients increased compared to normal serum IL-6 levels (7 pg/mL), patients with OD had significantly lower IL-6 levels (16.72 ± 14.28 pg/mL) than patients without OD (60.95 ± 89.33 pg/mL) (p = 0.026)." (PMID 37529051, 2023). "Underlying biological plausibility explaining these associations include anti-inflammatory markers, including IL-6, CRP, antioxidants, antithrombotic effects, and adhesion factors that are beneficial in COVID-19 prevention." (PMID 37748553, 2023). "We also explored the impact of IL-6 on T-cell tyrosine nitration and the expression of purinergic ectoenzymes in cultured peripheral blood mononuclear cells (PBMCs) from COVID-19 patients." (PMID 37818368, 2023). "IL-6 has been identified as a potential mediator of long-term neuropsychiatric symptoms of COVID-19." (PMID 37095536, 2023). "Among the 17 patients with severe COVID-19, the six patients who died exhibited significantly higher IL-6 levels compared with those who survived (486.2 ± 424.5 pg/mL vs. 98.6 ± 176.8 pg/mL, respectively; p = .035)." (PMID 37501590, 2023). "Patients with COVID-19 were treated with steroids (n = 74), IL-6-specific antibodies (n = 23), and remdesivir (n = 50)." (PMID 36740717, 2023). "Cytokines such as IL-6 and TNF-α, found in the serum of severe COVID-19 patients, cause decreased ATP production and abnormal generation of mtROS." (PMID 37869674, 2023). "Inflammatory mediators primarily associated with the cytokine storm in COVID-19 patients such as TNF-α, IL-1β, IL-6, IL-8, VEGF, and GM-SCF were elevated in both apical and basal media." (PMID 37200377, 2023).
COVID-19 (continued). "Regarding the inflammatory response, TNF-α, IL-1β, IL-6, GM-CSF, IL-8, IL-4, and IL-10 are involved in BA to alleviate COVID-19, ALI, PF, COPD, PAH, and asthma." (PMID 37007037, 2023). "As seen with the use of IL-6 targeting in COVID-19, the efficacy of any IL-6 therapy would depend on the severity of the disease and the timing of the intervention; as well as the ability to distinguish between IL-6 as a cause or a consequence of the disease." (PMID 37653422, 2023). "For example, the concentrations of IL-6 and IL-10 were higher on day 7 in severe COVID-19 patients compared to concentrations measured at onset." (PMID 36851312, 2023). "In this study, the level of a key indicator reflecting COVID-19 inflammation, serum IL-6 levels, were notably reduced in patients undergoing low-dose GCs therapy for NS as compared to those in the control group." (PMID 38274101, 2023). "Concomitantly, in severe COVID-19, an increase in the initial production of IL6 and IL10 (4/6 days) was seen and maintenance of high levels of CXCL8 at times 4/6 and 15/20 days." (PMID 37515295, 2023). "Increased cytokine levels (IL-6, IL-10, and TNF-α) and decreased IFN-γ expression in CD4+ T cells have been associated with severe COVID-19 in adults." (PMID 37602239, 2023). "In a large cohort of patients with COVID-19, systemic inflammation—as detected by increased levels of IL-6, hsCRP or ferritin—was highly correlated with the degree of ALI, as assessed by AST levels." (PMID 36986395, 2023). "Among the monoclonal antibody preparations used for COVID-19 pathogenetic therapy in children, IL-6, IL-1, TNF-alpha, and anti-IFNy receptor blockers are isolated." (PMID 37510846, 2023). "The researchers came to the conclusion that IL-6-blocking treatments have a greater likelihood of improving survival in COVID-19 patients who are hyper-inflamed when started before the onset of acute respiratory failure." (PMID 37759738, 2023). "Systemic inflammatory markers, such as IL-6 and CRP, were associated with disease severity and mortality among COVID-19 patients." (PMID 36744129, 2023). "It is, however, surprising that a recent metanalysis found a moderate IL-6 release in the innate immune response of patients with bacterial sepsis when compared to patients with COVID-19, and septic shock, with the presence of ARDS." (PMID 36979757, 2023). "As shown inTable 3, the chi-square test revealed a significant relationship between IL-6 levels and COVID-19 severity (P = 0.004; P <0.05)." (PMID 38099004, 2023). "Since the IL-6 seems to be related to respiratory failure, it can be considered as a biomarker of COVID-19 detection." (PMID 37754132, 2023). "The hyper-inflammatory response observed in COVID-19, manifesting as a cytokine storm, contributes to disease severity by increasing serum levels of IL-6, IL-8, TNF-α, and IL-1β." (PMID 37372128, 2023). "Severe COVID-19 cases in the study group showed greater levels of IL-6 than non severe patients (median = 48.8, P = .001)." (PMID 37960722, 2023). "Growth factor receptor-bound protein 2 (GBR2) is a receptor for interleukin-6 (IL6), whose serum levels significantly increase in COVID-19 patients." (PMID 36851954, 2023). "With the activation of TLR-7 and TLR-9 in COVID-19 mRNA vaccines, there are more alterations with pro-inflammatory cytokines such as interleukin 1 (IL-1) and interleukin 6 (IL-6)." (PMID 37091488, 2023). "Immune cell activation is reflected by high levels of IL-6, IL-1β, IL-18 known as the COVID-19 cytokine storm." (PMID 36776845, 2023). "About 65% of the COVID-19 patients showed hypovitaminosis D (less than 20 ng/mL) and elevated levels of the C-reactive protein, interleukin-6, tumor necrosis factor-α, d-dimers, and interleukin-10 markers." (PMID 36890344, 2023).